BIRC5 (baculoviral IAP repeat containing 5)
Description:
Multitasking protein that has dual roles in promoting cell proliferation and preventing apoptosis. Component of a chromosome passage protein complex (CPC) which is essential for chromosome alignment and segregation during mitosis and cytokinesis. Acts as an important regulator of the localization of this complex; directs CPC movement to different locations from the inner centromere during prometaphase to midbody during cytokinesis and participates in the organization of the center spindle by associating with polymerized microtubules. Involved in the recruitment of CPC to centromeres during early mitosis via association with histone H3 phosphorylated at 'Thr-3' (H3pT3) during mitosis. The complex with RAN plays a role in mitotic spindle formation by serving as a physical scaffold to help deliver the RAN effector molecule TPX2 to microtubules. May counteract a default induction of apoptosis in G2/M phase. The acetylated form represses STAT3 transactivation of target gene promoters. May play a role in neoplasia. Inhibitor of CASP3 and CASP7. Essential for the maintenance of mitochondrial integrity and function. Isoform 2 and isoform 3 do not appear to play vital roles in mitosis. Isoform 3 shows a marked reduction in its anti-apoptotic effects when compared with the displayed wild-type isoform.
Synonyms: API4; EPR-1; survivin
Tractability: Small molecule: a high-quality ligand is known; it has a binding pocket of medium quality; it belongs to a druggable protein family. PROTAC: UniProt records ubiquitination sites on it; ubiquitination databases record sites on it; a small molecule that binds it is known. Other modalities: a drug acting on it is in phase 2 or 3 trials.
Gene: Protein-coding gene on chromosome 17 (78,214,186 to 78,225,636, forward strand). Ensembl gene ENSG00000089685.
Subcellular location: Cytoplasm; Nucleus; Chromosome; Chromosome, centromere; Cytoplasm, cytoskeleton, spindle; Chromosome, centromere, kinetochore; Midbody
Subcellular location (Human Protein Atlas): Cytokinetic bridge
Pathways (Reactome):
Cell Cycle: Amplification of signal from unattached kinetochores via a MAD2 inhibitory signal; EML4 and NUDC in mitotic spindle formation; Mitotic Prometaphase; Resolution of Sister Chromatid Cohesion; Separation of Sister Chromatids
Metabolism of proteins: Neddylation; SUMOylation of DNA replication proteins
Immune System: Interleukin-4 and Interleukin-13 signaling
Signal Transduction: RHO GTPases Activate Formins
Gene Ontology:
Molecular function: enzyme binding; identical protein binding; protein binding; protein-folding chaperone binding; small GTPase binding; microtubule binding
Biological process: negative regulation of apoptotic process; negative regulation of DNA-templated transcription; protein-containing complex localization; sensory perception of sound; chromosome segregation; mitotic cell cycle; mitotic cytokinesis; mitotic spindle assembly; mitotic spindle midzone assembly; mitotic spindle organization; positive regulation of attachment of mitotic spindle microtubules to kinetochore; positive regulation of cell population proliferation; positive regulation of mitotic cell cycle spindle assembly checkpoint; positive regulation of mitotic cytokinesis; positive regulation of mitotic sister chromatid separation
Cellular component: chromosome; chromosome passenger complex; chromosome, centromeric region; cytoplasm; cytosol; intercellular bridge; kinetochore; microtubule cytoskeleton; midbody; nuclear chromosome; nucleus; survivin complex; nucleoplasm; spindle midzone; spindle
Genetic constraint (gnomAD): Loss-of-function variants: 7 observed, 13.1 expected, observed/expected ratio (o/e) 0.53, 90% interval 0.3 to 1. The upper end of that interval is the gene's LOEUF score, 1, which puts it in group 4 of 6, group 1 being the genes least tolerant of losing a copy. Missense variants: 145 observed, 156.95 expected, observed/expected ratio (o/e) 0.92, 90% interval 0.81 to 1.06. Synonymous variants: 49 observed, 57.31 expected, observed/expected ratio (o/e) 0.85, 90% interval 0.68 to 1.09.
Homologues: Orthologues: chimpanzee BIRC5 (99% identical), macaque BIRC5 (98% identical), pig BIRC5 (92% identical), guinea pig BIRC5 (87% identical), rat Birc5 (85% identical), mouse Birc5 (82% identical), tropical clawed frog birc5l (51% identical), zebrafish birc5a (50% identical), Drosophila melanogaster Diap2 (30% identical), Caenorhabditis elegans bir-2 (25% identical). Paralogues in human: BIRC2 (34% identical), BIRC3 (32% identical), NAIP (30% identical), XIAP (28% identical), NLRC4 (25% identical), BIRC7 (25% identical), BIRC6 (22% identical).
Diseases named in the same sentence as BIRC5 in open-access papers:
BIRC5 is named in the same sentence as 210 diseases in open-access papers, as found by Europe PMC text mining. Sharing a sentence is not in itself a finding about the gene and the disease. The quoted sentences say what the papers report.
breast carcinoma (118 papers, 2006 to 2025). "This study examines the association between three variants in the BIRC5 gene (rs8073069, rs17878467, and rs9904341) and breast cancer (BC) susceptibility." (PMID 40725442, 2025). "Our analysis of the BIRC5 promoter variants suggests that the variant rs8073069 (G/C) contributes to an increased susceptibility to breast cancer, particularly in individuals carrying the C/C genotype and the C allele." (PMID 40725442, 2025). "A comparative analysis of the BIRC5 rs8073069 G>C, rs17878467 C>T, and rs9904341 G>C variants in breast cancer (BC) patients and the control group revealed significant differences." (PMID 40725442, 2025). "In conclusion, our study demonstrates that the genotypes C/C of the rs8073069 variant, T/T of the rs17878467 variant, and G/C and C/C of the rs9904341 variant of the BIRC5 gene are associated with an increased risk of breast cancer." (PMID 40725442, 2025). "The aim was to analyze the rs8073069, rs17878467, and rs9904341 variants of the BIRC5 gene in patients with breast cancer to explore their potential as genetic risk markers in this population." (PMID 40725442, 2025). "The present study investigated the association between genetic variants in the promoter region of the BIRC5 gene and the risk of developing breast cancer in Mexican patients." (PMID 40725442, 2025). "Survivin/BIRC5 is a proliferation marker that is associated with poor prognosis in breast cancer and an attractive therapeutic target." (PMID 38515208, 2024). "Our findings also shed light on previously reported BIRC5 associations with breast cancer clinical outcomes, which have seldom been stratified by clinical subtype." (PMID 38515208, 2024). "High activity of BIRC5 has been associated with a poor prognosis and worse survival rates in breast cancer patients." (PMID 38755629, 2024). "In breast carcinoma, a marked increase in BIRC5 mRNA levels was observed, and its overexpression was linked to a deterioration in both overall and relapse-free survival rates." (PMID 39308922, 2024). "BIRC5 variants have consistently been implicated in a broad range of cellular behaviors, including breast cancer invasion." (PMID 35614362, 2022). "PIK3CA-BIRC5 was another reassuring pair as depletion of survivin (BIRC5) has been shown to have a pro-apoptotic effect in breast cancer cells with PIK3CA mutations." (PMID 36517508, 2022). "Increased expression of BIRC5 is a risk factor for cancer progression and poor outcomes in breast cancer." (PMID 35406376, 2022). "In the cited paper, the authors have shown that higher expression of the BIRC5 and BIRC7 genes is associated with higher tumor staging, and higher expression of the BIRC5 gene was associated with worse survival across breast cancers." (PMID 33673050, 2021). "Several studies have shown an association between BIRC5 overexpression and survival in breast cancer patients." (PMID 33673050, 2021). "The overexpression of these mRNAs (EpCAM,BIRC5 andYBXI) were all associated with poor outcomes for breast cancer patients." (PMID 33447385, 2020). "This was the first study investigating the possible role of BIRC5 polymorphisms in breast cancer etiology conducted in Croatia." (PMID 31467536, 2019). "The aim of this study was to investigate the role of BIRC5 polymorphisms in breast cancer (BC) and to connect survivin expression with various clinicopathological characteristics of BC patients." (PMID 31467536, 2019). "While known to be overexpressed in breast cancers, the relatively higher expression of BIRC5 observed among our high-risk patients (q = 1.37× 10−178) suggests there is a tipping point of mRNA abundance leading to increased risk." (PMID 28649643, 2017). "Analysis of the BIRC5 gene amplification and the comparison of changes with the age of onset of the disease showed a significant association between the breast cancer incidence in women under 40 years and an increase in BIRC5 copy number variation (P=0.04)." (PMID 27372966, 2016).
breast carcinoma (continued). "The copy number of BIRC5 has been indicated to be highly increased in tumor tissues; however, its association with the age of onset in breast cancer is not well understood." (PMID 27372966, 2016). "In the present study, the genomic copy number variation of BIRC5, which is supposed to be involved in breast cancer progression, was examined, and its association with the early-onset breast cancer was also evaluated." (PMID 27372966, 2016). "We found that increased BIRC5 expression is associated with advanced stage and ER− disease, but is prognostic only in ER+ breast cancer patients." (PMID 25763854, 2015). "Expression of BIRC5 is associated with a poor prognosis in a variety of malignancies, including breast cancer." (PMID 19007432, 2008). "Dysregulated BIRC5 have been linked to therapeutic resistance in stage II/III breast cancer." (PMID 35178302, 2022). "Similarly, high expression of BIRC5 was associated with overall survival in breast cancer, clear-cell renal cell carcinoma, gastric cancer, and lung cancer." (PMID 35309512, 2022). "Moreover, we previously evaluated BIRC5 in breast cancer subtypes, thereby demonstrating that high BIRC5 expression is associated with worse prognosis in breast cancer patients." (PMID 35331169, 2022). "Furthermore, RNA-splicing analysis reinforced the importance of BIRC5 splice variants in breast cancer metastasis." (PMID 35614362, 2022). "In addition to breast cancer, BIRC5 expression has been associated with prognosis and diagnosis of multiple other human cancers such as acute lymphoblastic leukemia, prolactinoma, pancreatic cancer and non-small cell lung cancer." (PMID 34712656, 2021). "Literature data indicate that high levels of the BIRC5 gene in breast cancer patients may be associated with resistance to treatment with paclitaxel, doxorubicin, and gemcitabine." (PMID 33673050, 2021). "This pioneering research, along with our bioinformatics analysis, would add a piece of evidence to the emerging idea that BIRC5 might contribute to breast cancer progression and drug resistance associated with CDC20 expression." (PMID 32043523, 2020). "Heatmap and DNA methylation status indicated that BIRC5 expression might be negatively associated with DNA methylation in breast cancer." (PMID 32043523, 2020). "Hence, this study was conducted to determine the association between BIRC5 genomic copy number variation and the age of onset in breast cancer." (PMID 27372966, 2016). "Up-regulation of BIRC5 is a frequent event in breast cancer, suggesting that BIRC5 may play an important role in tumorigenesis; furthermore, its expression in breast cancer tissue is significantly associated with poor clinical outcome." (PMID 22713668, 2012). "Additionally, BIRC5, a proliferation marker, is associated with poor prognosis in breast cancer." (PMID 40591061, 2025). "In addition, these findings may contribute to a more comprehensive understanding of the genetic mechanisms underlying breast cancer pathogenesis and BIRC5 susceptibility." (PMID 40725442, 2025). "These two cancer marker genes, MKI167 and BIRC5, have been reported to be highly expressed in cervical cancer in many studies, where they are associated with the cell cycle pathway and cell apoptosis inhibition, respectively, and are both involved in breast cancer pathogenesis." (PMID 34900703, 2021). "The results showed that BIRC5 is significantly overexpressed in breast cancer patients compared to normal breast tissue (p < 0.01)." (PMID 40725442, 2025). "There are two mRNA genes specified in this network (CDC25A and BIRC5) whose expression significantly correlated with upregulated miRNAs, namely hsa-mir-100 and hsa-mir-218-2, which are also known to be breast cancer drug targets." (PMID 40724805, 2025). "Consistent with previous findings, our analysis revealed BIRC5 overexpression across all breast cancer subtypes, reflecting a functional consequence of Hippo pathway inactivation that promotes tumor cell survival." (PMID 41153630, 2025).
breast carcinoma (continued). "Regarding in silico expression analysis, BIRC5 transcript levels were significantly elevated in breast carcinoma samples (TCGA-BRCA cohort) relative to normal mammary tissue (GTEx cohort; p < 0.01)." (PMID 40725442, 2025). "Downregulation of BIRC5 by siRNA decreased the viability of MCF7, MCF7-TamC3, and SK-BR-3 cells, highlighting the critical role of BIRC5 in the survival of the examined breast cancer cells." (PMID 39991577, 2025). "In breast cancer, high BIRC5 expression has been reported particularly in basal-like and luminal B subtypes, correlating with poorer patient survival independent of estrogen receptor status or lymph node involvement." (PMID 41153630, 2025). "In this analysis, BIRC5/survivin was investigated as a biomarker in two large studies representing 3269 patients with breast cancer, including TCGA and the CBCS, a large and diverse population-based study enriched for Black and younger patients." (PMID 38515208, 2024). "Next, to investigate the effect of loss of DAB2IP on NF-κB target genes, we selected SRSF1, and BIRC5, which are known to play important protumorigenic roles in breast cancer." (PMID 39418101, 2024). "BIRC5/survivin expression has also previously been reported as an independent marker of poor prognosis in breast cancer however, the findings of the current analysis extend those prior investigations to a large and diverse patient population." (PMID 38515208, 2024). "Our data also evidenced that some YAP/TAZ target genes, such as NF2, AXL, SOX2 and BIRC5, were regulated by Bcl-2 specifically in breast carcinoma model." (PMID 38755629, 2024). "In patients with HER2-overexpressing breast cancer, higher pretreatment survivin RNA levels correlated with poorer responses to trastuzumab, indicating BIRC5’s involvement in primary Herceptin resistance." (PMID 38534787, 2024). "Tetrachloroethylene ability to increase the expression of BIRC5 mRNA suggests deregulation of apoptosis as a potential mechanism affected by tetrachloroethylene in the development of breast cancer." (PMID 38982523, 2024). "We provide novel information on the fact that Haliclona fascigera extract exhibits anticancer properties against breast cancer via the activation of BIRC5, AKT1, MAPK, and TNFRSF1A genes." (PMID 37687120, 2023). "The upregulated expression of BIRC5 can be observed in many types of cancers, such as breast cancer and esophageal cancer." (PMID 38129460, 2023). "Other authors, in 2019, reported the detection of the biomarker BIRC5 (survivin) in dog serum, in primary culture of canine mammary tumor cells and in the canine mammary cancer cell line REM-134." (PMID 37893211, 2023). "BIRC5 splicing is frequently identified in breast cancers and has been suggested as a potential chemotherapeutic target." (PMID 35614362, 2022). "Kimia and colleagues uncovered a significant correlation between the increased copy number of BIRC5 and breast cancer individuals." (PMID 35461228, 2022). "For instance, BIRC5 was increased in triple-negative and BIRC5 knockdown significantly inhibits the proliferation of breast cancer cells, implying that BIRC5 acts like a tumor driver." (PMID 35309512, 2022). "Researchers showed that the BIRC5 gene was highly expressed in TNBC, and BIRC5 repression allowed the reduction of the proliferation of human breast cancer lines." (PMID 33673050, 2021). "We studied the BIRC5 protein level in tumor samples for breast cancer patients from a West Swedish cohort and its mRNA level in two different public gene expression databases." (PMID 34064473, 2021). "BIRC5 overexpression was reported in breast cancer, lung adenocarcinoma, and neuroblastic malignance specimens." (PMID 34497633, 2021). "UBE2T, UBE2C, and BIRC5 amplifications predicted a worse survival and poor response to therapy across different intrinsic subtypes of breast cancer." (PMID 33671201, 2021).